CD4 (CD4 molecule)
Diseases named in the same sentence as CD4 in open-access papers (continued):
Sharing a sentence is not in itself a finding about the gene and the disease.
fertility disorders (4 papers, 2008 to 2025). "Multiple authors reported an increase in the mean number of CD4+ cells in CT-infected women, compared with those with fertility disorders or controls." (PMID 41031366, 2025). "Real time RT-PCR analysis showed significant (P < 0.05) increase in IFN-γ mRNA in purified CD4+ T cells obtained from cervical cells and PBMCs in CT-positive fertile women compared to CT-positive women with fertility disorders." (PMID 19397832, 2009). "Interferon-gamma secreting cells and mRNA expression in inc-stimulated cervical and peripheral CD4 positive T cells were significantly higher (P < 0.05) in CT positive fertile women compared to CT-positive women with fertility disorders." (PMID 19397832, 2009). "Significant increase was seen in the mean number of CD4+ T-lymphocytes per 10,000 events in cervical mucosa of fertile women compared to women with fertility disorders and controls (2195 versus 401 and 262 respectively; P < 0.05)." (PMID 18828896, 2008). "Furthermore, lower cervical CD4+ T cell counts and differences in DC phenotypes have also been reported in women with fertility disorders." (PMID 41031366, 2025). "IL-4 and IFN-γ spot forming cells (SFCs) were enumerated in inc-stimulated CD4+ T cells purified from cervical cells and PBMCs in CT-positive women with and without fertility disorders and controls." (PMID 19397832, 2009). "CD4+ T cells in CT-positive fertile women exhibited significantly elevated numbers of IFN-γ SFCs, in a dose-dependent fashion, upon stimulation with 0.5 μg/ml or 1 μg/ml of both IncB and IncC, as compared to cells from CT-positive women with fertility disorders." (PMID 19397832, 2009). "CD4 Th1-IFN-γ producing cells are strongly involved in the protection from Ct infection and disease, whereas the role of CD8 Th1-cell population in the fertility disorders is not well defined." (PMID 22191045, 2011).
gastric diseases (4 papers, 2016 to 2018). "Using the dominant epitope of CD4 T cells, HpaA88-100, we have demonstrated that the immunodominant CD4 T cell response to HpaA88-100 reduced the risk of severe gastric diseases in an HLA-DRB1*1501-restricted population." (PMID 29552292, 2018). "The HpaA88-100 specific CD4+ T cell response was found to be associated with resistance to severe gastric diseases correlated to H. pylori infection in HLA-DRB1*1501 positive subjects." (PMID 27509059, 2016). "Here, we demonstrated that it was not the broad of peptide specificity, but the strength of HpaA specific CD4+ T cell responses was associated with gastric diseases potentially caused by H. pylori infection." (PMID 27509059, 2016). "We also demonstrated that it was not the broad peptide specificity, but the strength of HpaA specific CD4+ T cell responses associated with gastric diseases potentially caused by H. pylori infection." (PMID 27509059, 2016). "To verify whether such phenomenon existed during H. pylori infection, we evaluated the associations of HpaA specific CD4+ T cell response with gastric diseases potentially caused by H. pylori infection." (PMID 27509059, 2016). "It is known that pathogenic CD4+ T cells for the transfer EAE express cytokines including IFN-γ, IL-17A, and IL-6, and very strong stress alone induces gastric disease via p38 activation at the affected tissues by the activation of the vagal pathway." (PMID 28809157, 2017). "The immunodominant CD4+ T cell responses specific to HpaA88-100 were observed in most H. pylori infected individuals who expressed HLA-DRB1*1501 and were significantly more abundant in patients with less severe gastric diseases." (PMID 27509059, 2016).
gastric ulcer (4 papers, 2011 to 2020). An ulcerated lesion in the mucosal surface of the stomach. "Different from the immune response in gastritis, gastric ulcer is closely related to the distribution of gastric T cell subpopulations, which mainly performs in the ratio difference of CD4+/CD8+ T cell in the gastric mucosa." (PMID 32775468, 2020). "Of the 238 patients from the early HAART era, they identified odynophagia/dysphagia as an associated factor and an HIV-RNA viral load <400 copies/mL, a CD4+ cell count >200 cells/μl, and gastric ulcers as protective factors." (PMID 23555571, 2013). "In the HAART era, esophageal symptoms such as odynophagia and dysphagia are associated factors, while a CD4+ cell count >200, an HIV viral load <400, and the presence of gastric ulcers are considered protective factors for CE." (PMID 23555571, 2013). "Mortality rate was high in patients who had age ≥ 40 years, delayed presentation (>24 hrs), shock at admission (systolic BP < 90 mmHg), HIV positivity, low CD4 count (<200 cells/μl), gastric ulcers, concomitant diseases and presence of complications (P < 0.001)." (PMID 21871104, 2011). "A negative association with HLA-DRB1*1501 allele, reported in H. pylori-positive patients with gastric ulcers when compared with uninfected healthy controls, further supported this potential protective role mediated by HLA-DRB1*1501 restricted HpaA88-100 specific CD4+ T cell response." (PMID 27509059, 2016). "When gastric ulcer occurs, CD3+ T cells transform into CD4+ T cells and CD19+ B cells." (PMID 32775468, 2020). "According to the results of flow cytometry and immunohistochemistry, the number of CD19+ B cells, CD4+ Th cells, and CD8+ Tc cells in the gastric mucosa of gastric ulcer patients was higher than that of non-gastric ulcer patients." (PMID 32775468, 2020).
glomerulosclerosis (4 papers, 2020 to 2024). A hardening of the kidney glomerulus caused by scarring of the blood vessels. "Compared to the vehicle control mice, Ac-FLTD-CMK-treated MRL/lpr mice had a lower urine albumin-creatinine ratio, a lower serum creatinine concentration, reduced glomerulosclerosis and CD3, CD4 and CD68 positive cell infiltration." (PMID 34867948, 2021). "Surprisingly, the number of infiltrating CD4 + CD28− T cells was negatively correlated with the estimated glomerular filtration rate (eGFR), but positively correlated with proteinuria, the proportion of glomerulosclerosis and the degree of chronicity of the LN renal tissue." (PMID 36320075, 2022). "Immunofluorescence showed CD4 + CD28− T cell infiltration in the kidney of LN patients, which was correlated with multiple clinicopathological features including estimated glomerular filtration rate (eGFR), proteinuria, the proportion of glomerulosclerosis and the degree of renal chronicity." (PMID 36320075, 2022).
Hemophagocytosis (4 papers, 2019 to 2024). Phagocytosis by macrophages of erythrocytes, leukocytes, platelets, and their precursors in bone marrow and other tissues. "Bone marrow aspirate showed hypocellularity and hemophagocytosis, and the bone marrow biopsy confirmed a bone marrow localization of CD3+, CD8+, CD4−, CD5+, and CD20− peripheral T lymphoma." (PMID 38892108, 2024).
hemorrhagic fever (4 papers, 2010 to 2023). An infectious disease caused by certain viruses or bacteria that can damage the walls of tiny blood vessels, making them leak, and can hamper the blood's ability to clot and cause severe, life-threatening illness. "Here, based on the T-cell epitopes mapped on HTNV glycoprotein, we studied the effects and characteristics of CD4+T-cell responses in determining the outcome of hemorrhagic fever with renal syndrome." (PMID 25836633, 2015). "In conclusion, the identification of CD4+ and CD8+ T cell epitopes from 7 different arenavirus species might lead to the development of a T cell-based vaccine strategy protecting against Old and New World arenavirus infection responsible for hemorrhagic fever and aseptic meningitis in humans." (PMID 20478058, 2010).
Hepatomegaly (4 papers, 2010 to 2025). Abnormally increased size of the liver. "Accordingly, we demonstrated that the F3 peptide vaccine was capable of increasing the IDR and the ratios of TNF-α/IL-10 CD4+ T cells and of decreasing the parasite load and hepatomegaly." (PMID 21085470, 2010). "Also similar to what has already been reported the ratios of IFN-γ/IL-10 producing CD4 T cells were not correlated to the decrease of LDU or hepatomegaly (p>0.05), but were correlated to the increase of IDR, CD4+ T cells and IgG, IgG2a and IgG2b antibodies (p<0.023 for all variables)." (PMID 21085470, 2010).
hereditary hemochromatosis (4 papers, 2019 to 2024). An inherited metabolic disorder characterized by iron accumulation in the tissues. "Moreover, the primary haemochromatosis study in Porto showed a positive correlation between iron load and CD4/CD8 ratio, and a negative correlation between iron load and CD8." (PMID 34239727, 2021).
herpetic keratitis (4 papers, 2019 to 2023). "While complement C3 and antigen-specific CD4+ T cells appear to coordinate corneal sensation loss in herpetic keratitis, it remained to be determined whether this phenomenon was specific to HSV-1 infection." (PMID 31414985, 2019). "The pharmacologic impact of local CVF treatment on ocular GVHD progression was consequently explored in order to identify whether the CD4+ T cell-associated corneal sensation loss observed in both herpetic keratitis and ocular GVHD shared a common C3-codependent pathomechanism." (PMID 31414985, 2019). "In herpetic keratitis, the specificity of CD4+ T cells is relevant because HSV1-infected mice that only harbor CD4+ T cells reactive against an irrelevant antigen do not develop sensory neuropathy." (PMID 37217914, 2023). "More recently, it was shown that in herpetic keratitis, both CD4+ T cells and myeloid cells secrete high levels of vascular endothelial growth factor-A, which is pathogenic to corneal nerves." (PMID 37217914, 2023). "In summary, these preclinical models establish that CD4+ T cells and complement C3 coordinate corneal sensory nerve damage in both herpetic keratitis and ocular GHVD." (PMID 31414985, 2019). "However, in murine models of herpetic keratitis and ocular GVHD, complement activation and CD4+ T cells targeting disease-specific pathogenic antigens (viral proteins or allogeneic peptides) have been shown to promote corneal nerve damage." (PMID 37217914, 2023). "Corneal nerve retraction in herpetic keratitis can occur in the absence of CD4+ T cells, although only transiently." (PMID 37217914, 2023). "By comparing different murine models of ocular surface disorders, they found that CD4+ T cells promote corneal nerve damage in herpetic keratitis and ocular graft-versus-host disease but not in ocular allergy." (PMID 37217914, 2023). "The exact role of the CD4+/CD8+ TRM axis in the trigeminal ganglia and/or cornea in controlling recurrent herpetic keratitis is unknown." (PMID 33668777, 2021).
histiocytic sarcoma (4 papers, 2012 to 2025). An aggressive malignant neoplasm with a poor response to therapy, usually presenting as stage III/IV disease. "The expression level of CTLA-4 on CD4+ lymphocytes was significantly higher in the histiocytic sarcoma group than in the control group." (PMID 26901565, 2016). "The expression level of CTLA-4 on CD4+ lymphocytes was significantly higher in the histiocytic sarcoma group (mean ± standard deviation: 3.20% ± 1.74%) than in the control group (1.27% ± 0.79%; P = 0.048)." (PMID 26901565, 2016). "Histiocytic sarcoma (HS) is an extremely rare hematopoietic neoplasm that originates from the macrophage lineage and shows a sarcoma‐like spread of CD4+, CD68+, PU.1+, and CD163+ histiocytic cells." (PMID 40938275, 2025). "CTLA-4 expression was significantly increased on CD4+ and CD8+ lymphocytes in the histiocytic sarcoma group." (PMID 26901565, 2016). "The present results provided evidence showing that the expression levels of CTLA-4 on both CD4+ and CD8+ lymphocytes and PD-1 on CD8+ lymphocytes in peripheral blood obtained from dogs with histiocytic sarcoma were upregulated." (PMID 26901565, 2016). "In conclusion, the present study demonstrated upregulation of CTLA-4 expression on both CD4+ and CD8+ T cells and PD-1 expression on CD8+ T cells in peripheral blood obtained from dogs with histiocytic sarcoma." (PMID 26901565, 2016).
HIV infection (4 papers, 2008 to 2018). "T-cell activation isbelieved to be the major cause of CD4+ T-cell depletion in HIV infection,through a progression of activation-induced cell death (AICD)." (PMID 18695741, 2008). "Our data show that expression of PD-1 onearly-differentiated CD4 T cells may represent a population that is highlyfunctional, more susceptible to HIV infection and selectively lost in chronic HIVinfection." (PMID 26678998, 2015). "Collectively, our data suggest that theseearly-differentiated CD4 T cells may be more susceptible to HIV infection due toincreased activation and increased co-expression of CCR5 and PD-1." (PMID 26678998, 2015). "We further analyzed the phenotype and function ofPD-1highCTLA-4lowCD127high EI CD4 T cells and foundthat PD-1 expression was associated with increased activation, measured by HLA-DR andCD38 expression and increased susceptibility to HIV infection, based on the expressionof the HIV co-receptor CCR5." (PMID 26678998, 2015). "We propose that thedynamics of CD4 T cells may be altered by their susceptibility to HIV infection(PD-1highCD127highCD4 T cells) and the skewed maturation ofHIV-specific CD4 T cells (PD-1highCD127low), which arepreferentially infected and highly sensitive to viral load changes and TCRstimulation." (PMID 26678998, 2015). "CD4 T-cell counts were documented in 59% of those with reported HIVinfection, and median CD4 count were 311 cells/mL3 (IQR, 124 to 503cells/mL3)." (PMID 30241139, 2018). "To further investigate the impact of HIV infection on the described CD4 T cellpopulations, we combined data for HIV-infected subjects from Cohorts 1 and 2, beforetreatment (n = 45)." (PMID 26678998, 2015). "We have previously shown that CD4 T cells expressing aCCR7highCXCR5highCCR6highPD-1highphenotype can provide increased in vitro B cell help and isdecreased in HIV infection." (PMID 26678998, 2015). "HIV infection induced a decrease in CD4+ T-cell numbers and concomitantly activated the immune system." (PMID 18695741, 2008). "Our data suggest thatincreased expression of CCR5 on an activated background could result in the increasedsusceptibility of PD-1highCD127high EI CD4 T cells to HIVinfection." (PMID 26678998, 2015). "Ourdata indicate that PD-1highCD127high EI CD4 T cells may bepreferentially lost during chronic HIV infection." (PMID 26678998, 2015). "Overall, our data indicate that PD-1 and CTLA-4 could serve as a very early marker ofdifferentiation of CD4 T cells during HIV infection marking cells with increasedsensitivity to infection." (PMID 26678998, 2015). "Previous studies have shown that CD4 TFH cellswithin lymph nodes may be the major reservoir for HIV infection and replication." (PMID 26678998, 2015). "HIV infection wasassociated with greater expression of HLA-DR/CD38 and lower expression of CD28on CD4+ and CD8+ T-cells." (PMID 18695741, 2008). "The role of PD-1 expression on CD4 T cells during HIV infection is not wellunderstood." (PMID 26678998, 2015).
Hydrocephalus (4 papers, 2017 to 2024). Hydrocephalus is an active distension of the ventricular system of the brain resulting from inadequate passage of CSF from its point of production within the cerebral ventricles to its point of absorption into the systemic circulation. "Here we show that α-SNAP hypomorph, hydrocephalus with hopping gait, Napahyh/hyh mice harbor significant defects in CD4 T cell gene expression and Foxp3 regulatory T cell (Treg) differentiation." (PMID 28492364, 2017).
Hyperammonemia (4 papers, 2014 to 2026). An increased concentration of ammonia in the blood. "They suggest that possible reason for CD4 down-regulation in their study could be due to the immunosuppressive effect, which results from hyperammonemia in infected CEV carp." (PMID 37465154, 2023). "It is unclear whether the down-regulation of cd4 and igm transcription in KSD-affected koi depended on an immunosuppressive effect of hyperammonemia in carp." (PMID 34269137, 2021).
Hyperbilirubinemia (4 papers, 2021 to 2024). An increased amount of bilirubin in the blood. "Endotoxins and hyperbilirubinemia may act on T cells and cause a decrease in the number of CD4+ T cells." (PMID 38710890, 2024). "CD3+ and CD4+ T cell SCMM values were positively correlated with the serum bilirubin levels, and might correlated with hyperbilirubinemia risk." (PMID 37397145, 2023). "This study suggested that the mitochondrial CD3+, CD4+, and CD8+ SCMM parameters differed among jaundiced neonates with different hyperbilirubinemia risks." (PMID 37397145, 2023).
hyperplasia (4 papers, 2011 to 2017). An abnormal increase in the number of cells in an organ or a tissue with consequent enlargement. "One of these patients had Histoplasma capsulatum detected on both histological analysis and fungal culture (patient HIV positive with a CD4 count of 28 cells/mm3), and one patient was assigned a diagnosis of hyperplasia." (PMID 29031289, 2017).
hypopharyngeal carcinoma (4 papers, 2020 to 2023). Carcinoma, predominantly squamous cell, arising from the epithelial cells of the hypopharynx. "The proportions of CD4 + T memory resting cells and mast cells appeared to be drastically different between laryngeal and hypopharyngeal cancer." (PMID 33173143, 2020). "γδT cells in paracancerous tissues of HSCC patients were significantly more abundant than that in hypopharyngeal carcinoma tissues, while CD8+ T cells and naïve CD4+ T cells in cancer tissues were higher than those in paracancerous tissues." (PMID 37182154, 2023). "In contrast, neither high CD4+ nor CD8+ TILs were associated with improved OS for oral cavity, laryngeal or hypopharyngeal cancers." (PMID 33668519, 2021).
hypovitaminosis D (4 papers, 2013 to 2024). "According to the literature, hypovitaminosis D is associated with decreased CD4 counts and increased viral loads." (PMID 38373939, 2024). "The estimated duration of the HIV infection was also associated with hypovitaminosis D (p = 0.0008), whereas the HIV CDC stage, current and nadir CD4, HIV viral load, and time spent on the current ARV (by specific drug or overall), and the duration with undetectable HIV viral load were not." (PMID 23295013, 2013). "Treatment of SLE patients with hypovitaminosis D with 100,000 U of VitD3 weekly for 4 weeks and then monthly for 6 months resulted in an increase in naïve CD4+ T cells and CD3+CD4+CD25hiCD127–Foxp3+Tregs and decreases in CD19+ B cells, anti-ds DNA antibody titers, and proteinuria." (PMID 26106387, 2015).
imbalance (4 papers, 2021 to 2025). "In our study, the reduction of CD4+/CD8+ ratio and consequently the immune imbalance was more prominent in RS than in AS." (PMID 33717146, 2021). "According to our results, agranulocytosis, attenuation of CD4+ and CD8+ T-cell, humoral immune imbalance, pancreatic and renal damage can predict the occurrence of IPA." (PMID 34025635, 2021). "Flow cytometric analysis demonstrated a significantly lower CD4+/CD8+ ratio in the RPBB group compared to the CG group (median [IQR]: 1.15 [0.98–1.31] vs. 1.54 [1.42–1.69], P = 0.003), indicating a potential immune imbalance in RPBB." (PMID 40792104, 2025).
infectious colitis (4 papers, 2015 to 2023). A viral or bacterial infectious process affecting the large intestine. "Accordingly, most of the IL-22-producing CD4 T cells of lamina propria co-express T-bet during infectious colitis." (PMID 28408906, 2017). "In a model of Citrobacter rodentium-driven infectious colitis, IL-33 inhibited the differentiation of IL-17A-producing CD4+ T cells, which have the potential to reverse the negative effect of IL-33 during infection." (PMID 36570798, 2022).